STAT3 (signal transducer and activator of transcription 3)
Diseases named in the same sentence as STAT3 in open-access papers (continued):
Sharing a sentence is not in itself a finding about the gene and the disease.
gastric cancer (continued). "In addition, NF-κB and STAT3 can synergistically influence the metastatic potential of gastric cancer cells through regulation of MMP-9 expression." (PMID 28350359, 2017). "Furthermore, previous reports indicated that pantoprazole can inhibit astrocytes and gastric cancer cells as well as the phosphorylation level of STAT3." (PMID 28489606, 2017). "We further examined whether block the JAK2/STAT3 pathway by AG490 could also inhibit the tumor-promoting effects on gastric cancer cells via the secretion of IL-6 by CAFs." (PMID 28186964, 2017). "Moreover, co-ordinated high expression of SIRT1 and STAT3 predicted poor overall survival for advanced gastric cancer patients." (PMID 28061480, 2017). "The AKT-NFκB and STAT3 signaling pathways can upregulate DNMT1 expression, which could cause aberrant DNA methylation of tumor suppressor genes and lead to gastric cancer." (PMID 28473984, 2017). "Previous studies have demonstrated that STAT3 is activated in gastric cancer tissues." (PMID 28186964, 2017). "Finally, we confirm CD163 is a novel target gene of STAT3 (signal transducer and activator of transcription 3) in gastric cancer." (PMID 29152078, 2017). "Also, as expected, the expression levels of SIRT1 and STAT3 mRNA were significantly higher in gastric cancer tissues than in matched normal mucosa from public datasets." (PMID 28061480, 2017). "The expression of miR-847 is decreased in gastric cancer, which activates the signal transducer and activator of transcription 3 (STAT3)/vascular endothelial growth factor A (VEGF-A) pathway, increases tumor angiogenesis, and promotes the development and progression of gastric cancer." (PMID 27464701, 2016). "To identify STAT3 targets that are differentially expressed through the activation of STAT3 in gastric cancer, we performed RNA sequencing (RNA-Seq) by using 23 pairs of gastric cancer patient samples." (PMID 27598141, 2016). "Our group found that TGR5 activation could suppress gastric cancer cell proliferation and migration via inhibiting STAT3 pathway." (PMID 28082913, 2016). "We hypothesized that HCCR might modulate cell proliferation and apoptosis by regulating the activation of STAT3 in gastric cancer cells." (PMID 27052330, 2016). "Furthermore, the relationship among Notch, STAT3, and Twist1 pathways in the control of tumor progression was studied, and the results suggested that Notch1/STAT3/Twist signaling axis is involved in progression of human gastric cancer." (PMID 26823670, 2016). "Here, we provide evidence showing that acquisition of trastuzumab resistance is associated with the formation of EMT/CSC phenotype and transition of survival signaling through activating IL-6/STAT3/Jagged-1/Notch positive feedback signaling loop in gastric cancer cells." (PMID 25669984, 2015). "Furthermore, it is found that TGR5 activation antagonizes STAT3 signaling in gastric cancer cells through inhibiting STAT3 transcriptional activity and phosphorylation." (PMID 26417930, 2015). "In this study, as the majority of bacterial pathogens mediate STAT3 activation via autocrine IL-6, it was found that IL-6 expression was increased after H. pylori infection, and both IL-6 and IL-11 were strongly up-regulated in gastric cancer tissue." (PMID 26160167, 2015). "The present data indicate that the curcumin analog GO-Y031 may be a promising lead agent for the treatment of gastric cancer, acting as a β-catenin and/or STAT3 inhibitor." (PMID 25331984, 2015).
gastric cancer (continued). "Furthermore, there is an inverse association between RKIP and Stat3 expression in gastric cancer tissues, and the high expression of cytoplasmic RKIP and nuclear Stat3 is correlated with poor patient prognosis." (PMID 25915430, 2015). "A previous study utilized STAT3 inhibitor to treat gastric cancer and showed efficacy." (PMID 25646628, 2015). "Moreover, in a mouse model of gastric cancer, STAT3 activation promoted carcinogenesis via Toll-like receptor 2 without inflammatory signaling." (PMID 25331984, 2015). "STAT3 and pSTAT3 signals were abundantly observed in gastric cancer tissues." (PMID 25331984, 2015). "Next, we compared gastric carcinoma patients with those with gastritis in order to evaluate the number of EPIYA-C segments as a predictor of gastric cancer as well as the co-participation of the bacterial EPIYA-C segments and STAT3 polymorphism in the risk of the disease." (PMID 26186918, 2015). "We have shown that STAT3 is constitutively activated in human gastric cancer, and that chronic IL-11-driven STAT3 transcriptional activity induces gastric tumourigenesis in the gp130757FF mouse model of gastric cancer development." (PMID 24804649, 2014). "H. pylori infection triggers the activation of STAT3 and de-regulates multitude of tumorigenic genes which may contribute to the initiation and progression of gastric cancer." (PMID 25594045, 2014). "In gastric cancer, activation of STAT3 via the EGFR signaling pathway may contribute to tumor progression by increasing lymph node metastasis of the tumor." (PMID 24662939, 2014). "Next, we analyzed the significance of STAT3 activation in gastric cancer cells." (PMID 23593346, 2013). "Constitutive activation of STAT3 is predictive of poor prognosis in human gastric cancer." (PMID 24116074, 2013). "Similarly, inhibition of IL-6 pathway abrogated Stat3-mediated cell survival of gastric cancer and osteosarcoma, suggesting the importance of IL-6 in promoting tumor growth." (PMID 23922669, 2013). "To further confirm the increased expression of STAT3, p-STAT3, IL-6, survivin and VEGF in gastric cancer tissues, we also performed western blotting to determine their levels using anti-STAT3, anti-phosphorylated STAT3 (Tyr705), anti-IL-6, anti-survivin, anti-VEGF antibodies, respectively." (PMID 24116074, 2013). "Furthermore, we evaluated the expression of AFP and STAT3 by immunohistochemistry in human gastric cancer samples." (PMID 23382965, 2013). "The STAT3 staining was mainly localized in the nuclei of gastric cancer cells." (PMID 24116074, 2013). "It remains unclear whether increased IL-6/STAT3 activation correlates with aberrant immunity in the progression and invasion of gastric cancer." (PMID 24116074, 2013). "Thus, in this specific type of gastric cancer, STAT3 appears to have an important role in cell survival and proliferation." (PMID 23382965, 2013). "Notably, our results for the first time demonstrated that calpain/SHP-1 interaction is directly triggered by honokiol inhibition of STAT-3 phosphorylation in gastric cancer cells." (PMID 22937084, 2012). "In this study, we examined the efficacy of NVP-BKM120, a pan-class I PI3K inhibitor in human gastric cancer cells and hypothesized that the combined inhibition of PI3K and STAT3 would be synergistic in KRAS mutant gastric cancer cells." (PMID 22159814, 2012). "Together, these findings suggest for the first time that the dual inhibition of PI3K and STAT3 signaling may be an effective therapeutic strategy for KRAS mutant gastric cancer patients." (PMID 22159814, 2012). "Since there is an inverse relationship between RKIP and STAT3 expression in gastric cancer specimens, we evaluated whether STAT3 and its key regulator IL-6 affects pRKIP expression." (PMID 22662230, 2012). "PI3K blockade in combination with STAT3 inhibitors may benefit patients with gastric cancer exhibiting oncogenic KRAS." (PMID 22159814, 2012).
gastric cancer (continued). "Because of the important roles of RKIP, STAT3 and H. pylori in the pathogenesis of gastric cancer, we investigated whether H. pylori signals through RKIP." (PMID 22662230, 2012). "Here, we hypothesized that honokiol inhibits the angiogenesis and peritoneal dissemination of gastric cancer cells through a calpain/SHP-1-regulated STAT-3 and VEGF pathway." (PMID 22937084, 2012). "We have therefore now investigated whether activation of MET contributes to STAT3 activation and further examined the roles of STAT3 in human gastric cancer cell lines." (PMID 21730976, 2011). "To examine whether the activation of MET contributes to STAT3 activation, we determined the effects of the MET-TKI PHA-665752 on the phosphorylation of STAT3 in gastric cancer cells with STAT3 activation." (PMID 21730976, 2011). "To examine whether IL-6 contributes to STAT3 activation in gastric cancer cells, we first measured the secretion of IL-6 from such cells with the use of an ELISA." (PMID 21730976, 2011). "Strategies that target STAT3 signalling may thus provide novel approaches to gastric cancer intervention." (PMID 21730976, 2011). "Furthermore, activated STAT3 contributes to either survival or cell motility depending on the mechanism of its activation in gastric cancer cell lines." (PMID 21730976, 2011). "Aberrant activation of STAT3 has been proved to play a critical role in gastric cancer development." (PMID 20939893, 2010). "In the present study, we demonstrated that isoproterenol stimulation prominently induced the activation of STAT3 in gastric cancer cells, implicating that catecholamine may accelerate the malignant progression of gastric cancer." (PMID 20939893, 2010). "The increase of STAT3 activity together with overexpression of cytokine in this gastric cancer cell line suggested that alteration of JAK/STAT was important in a subset of gastric cancer." (PMID 15354212, 2004). "In recent years, multiple studies have demonstrated that CuB exerts anticancer effects in non-small cell lung cancer (NSCLC) and gastric cancer (GC) by targeting STAT3." (PMID 41145734, 2025). "This study provides evidence that the combination of DZN and PNR effectively inhibits the proliferation of gastric cancer (GC) cells by targeting the STAT3/FAK signaling pathway." (PMID 40217305, 2025). "Furthermore, in gastric cancer cells, VPS35 expression is upregulated, and it positively regulates the proliferation and peritoneal metastasis of gastric cancer cells through integrin/FAK/SRC signalling-mediated IL-6/STAT3 pathway activation in a YAP-dependent manner." (PMID 40484931, 2025). "Prior research has demonstrated that inhibiting activated STAT3 can stop chemotherapy-induced resistance within human gastric carcinoma cells, and that focusing on stomach epithelial STAT3 specifically may be therapeutically efficient at hindering the development of gastric cancer." (PMID 40350446, 2025). "The JAK2/STAT3 pathway is also activated by stem cells in GC through high secretion of IL-6/IL-8, and this contributes to M2-like TAM polarization and, consequently, promotes gastric cancer metastasis." (PMID 38542388, 2024). "Additionally, the deployment of neutralizing antibodies to deplete IL-6 or the application of the specific inhibitor AG490 to impede the JAK/STAT3 pathway significantly mitigates these CAF-induced phenotypic traits in gastric cancer cells and curtails their metastatic propensity." (PMID 39309860, 2024). "Moreover, through the activation of STAT3, Hp-I deregulates multiple tumorigenic genes, which may contribute to the initiation and progression of gastric cancer." (PMID 38883131, 2024). "Moreover, neutrophils enhance the migration, invasion and EMT of gastric cancer cells through the IL-17a/JAK2/STAT3 signaling, meanwhile blocking the IL-7a or disrupting the JAK2/STAT3 signaling increase the tumor cytotoxicity of neutrophils against the cancer." (PMID 38245798, 2024).
gastric cancer (continued). "In addition, DARPP-32 activates IGF1R and STAT3 signaling in gastric cancer cells." (PMID 38233872, 2024). "The signaling landscape upstream of STAT3 consists of several modulators, including noncoding RNAs and small proteins, which control gene expression and epigenetic frameworks either by activating or inhibiting STAT3, thus affecting the development of gastric cancer." (PMID 39309860, 2024). "Considering that the level of DARPP-32 increases along with positive STAT3 nuclear immunostaining in gastric cancer tissues, the DARPP-32-IGF1R signaling axis might act as a critical regulator of STAT3 signaling and play an important role in gastric tumorigenesis." (PMID 39309860, 2024). "Considering the preliminary success of CAR-T-cell therapy in treating gastric cancer, future strategies might include employing genetic engineering to knock out or silence the STAT3 gene in CAR-T cells before they are reinfused into patients with gastric cancer." (PMID 39309860, 2024). "Similarly, the transcription of the long noncoding RNA (lncRNA) NEAT1 increases considerably in gastric cancer cells; this increase is similar to the increase in the expression of STAT3 and is correlated with an increase in neoplastic proliferation and invasion capacity." (PMID 39309860, 2024). "Drug-resistant gastric cancer-cell lines such as SGC7901/DDP, BGC823, and HGC27 exhibit higher activation of STAT3 compared to drug-sensitive GC cell lines." (PMID 38474604, 2024). "Therefore, PA alters STAT3 protein levels in human gastric cancer cells." (PMID 36672337, 2023). "We also examined the OCR curve of gastric cancer cells after treatment with compound 4, which indicated that compound 4 could affect the mitochondrial respiration of gastric cancer cells by inhibiting STAT3." (PMID 38023173, 2023). "Thus, this study aimed to identify novel STAT3 inhibitors that may broaden the therapeutic arsenal for gastric cancer treatment." (PMID 38023173, 2023). "Consequently, our study suggests that the GDF15/STAT3 signaling axis may be an effective prognostic target for patients with gastric cancer." (PMID 36769245, 2023). "A study on AGS, SNU-1, and HGC-27 gastric cancer cell lines revealed that the activation of NF-κB occurred in H. pylori infection, which again triggered the activation of another pro-inflammatory transcription factor—signal transducer and activator of transcription 3 (STAT3)." (PMID 37508393, 2023). "Our data showed that SDL-1 induced STAT3 protein degradation while inhibiting the growth activity of gastric cancer cells in vitro, suggesting that it could be used as a potential anti-gastric cancer drug and providing a new strategy for gastric cancer therapy." (PMID 36034876, 2022). "DYNC1I1, the binding subunit of cytoplasmic dynein, could assist the cytoplasmic dynein-mediated transport of P65 to the nucleus, following which P65 could promote the expression of IL-6 and activate the STAT3 phosphorylation to promote the proliferation and metastasis of gastric cancer cells." (PMID 35002514, 2022). "Previous results suggested that β2-AR could pass STAT3 to promote EMT in gastric cancer cells." (PMID 35517411, 2022). "Therefore, we speculate that EVs-L-PGDS may inhibit the gastric cancer progression by inhibiting STAT3 phosphorylation." (PMID 35087591, 2022). "A previous study reported that the STAT3 signaling pathway was involved in the EXOSC5-regulated proliferation of gastric cancer, and the elevated phosphorylation of STAT3 was also shown in HCC tissues and cell lines, which could be inhibited by the down-regulation of EXOSC5 in the present study." (PMID 36293016, 2022). "And NR4A3 could activate STAT3 to inhibit the progression of gastric cancer." (PMID 35747513, 2022).
gastric cancer (continued). "Similarly, cancer-associated fibroblasts (CAF) in the tumor microenvironment promote the progression of gastric cancer through IL-6/JAK2/STAT3 signaling and achieve a targeted therapeutic effect on gastric cancer through the action of IL-6 on stromal fibroblasts." (PMID 35528617, 2022). "For instance, in gastric cancer (GC), tumor-derived GM-CSF induced PD-L1 expression on neutrophils, via Jak-Stat3 signaling pathway, suppressing T-cell immunity and contributing to GC progression." (PMID 36016960, 2022). "Further in vivo investigations verified that the combination treatment of circUBE2Q2 knockdown and STAT3 inhibitor had synergistic effects on the inhibition of gastric cancer growth, suggesting that targeting circUBE2Q2 may increase the sensitivity of targeted therapies to gastric cancer." (PMID 36386850, 2022). "Higher NR4A3 methylation could be observed in gastric cancer patients with STAT3 activation." (PMID 33886682, 2021). "This study found that SLCO4A1-AS1 has a cancer-promoting effect in gastric cancer cells, which may regulate the biological characteristics of gastric cancer cells by targeting STAT3 with miR-149-5p, suggesting that SLCO4A1-AS1 may be used for the treatment of gastric cancer." (PMID 34712324, 2021). "Besides, methylation of this potential STAT3 target may serve as a marker for the response and efficacy of targeting STAT3 in gastric cancer, as it may respect to STAT3 activity in early carcinogenesis." (PMID 33886682, 2021). "Targeted inhibition of STAT3 may be a novel therapeutic strategy against gastric cancer." (PMID 33718136, 2021). "TQ treatment inhibits signal transducer and activator of transcription-3 (STAT3) phosphorylation, causing downregulation of STAT3 and its related genes, Janus activated kinase-2 (JAK2), c-Src, Bcl-2, cyclin D, survivin, VEGF and caspases 3, 7 and 9 in gastric cancer." (PMID 33540625, 2021). "In gastric cancer (GC), tumor-derived GM-CSF activates neutrophils and induces PD-L1 expression on neutrophil via Jak-Stat3 signaling pathway, therefore inhibiting T-cell immunity and contribute to the GC progression." (PMID 33101283, 2020). "Thus, RNF180 may be a potential candidate for GC treatment, illustrating that RNF180 has an important role in gastric cancer and its propagation by modulating the phosphorylation state of STAT3." (PMID 33082325, 2020). "In addition, lncRNA PVT1 promotes angiogenesis via STAT3/VEGFA axis in gastric cancer." (PMID 32600379, 2020). "A recent study on GC has shown that C3 deposited in the tumor microenvironment can independently activate the JAK2/STAT3 pathway, and promote tumor progression, indicating its potential as a prognostic factor for patients with gastric cancer." (PMID 33193896, 2020). "Additionally, piperine inhibited STAT3 in TMK-1 gastric cancer cell line." (PMID 32669593, 2020). "Therefore, the novel OL8/IL‐11/STAT3 signaling axis may enrich our understanding of mechanisms of gastric cancer progression." (PMID 31273847, 2019). "The fact that TFF1 is silenced in the majority of human gastric cancers by genetic, epigenetic, and transcription mechanisms highlights the importance of our results and denotes a previously unknown protective function of TFF1 against the oncogenic activation of STAT3 in gastric cancer." (PMID 31292446, 2019). "Therefore, we can conclude that STAT3 might be able to pass through membrane structures between gastric cancer stem cells and Treg/CD4+ uncommitted T cells to change the shift them to Th17 cells." (PMID 31024835, 2019). "Interestingly, Yang et al30 have reported that acquisition of trastuzumab resistance is associated with the formation of the EMT/CSC phenotype and transition of survival signalling through activating an IL‐6/STAT3/Jagged‐1/Notch positive feedback signalling loop in gastric cancer cells crosstalk." (PMID 30993885, 2019).